BICD2 (BICD cargo adaptor 2)
Description:
Acts as an adapter protein linking the dynein motor complex to various cargos and converts dynein from a non-processive to a highly processive motor in the presence of dynactin. Facilitates and stabilizes the interaction between dynein and dynactin and activates dynein processivity (the ability to move along a microtubule for a long distance without falling off the track). Facilitates the binding of RAB6A to the Golgi by stabilizing its GTP-bound form. Regulates coat complex coatomer protein I (COPI)-independent Golgi-endoplasmic reticulum transport via its interaction with RAB6A and recruitment of the dynein-dynactin motor complex. Contributes to nuclear and centrosomal positioning prior to mitotic entry through regulation of both dynein and kinesin-1. During G2 phase of the cell cycle, associates with RANBP2 at the nuclear pores and recruits dynein and dynactin to the nuclear envelope to ensure proper positioning of the nucleus relative to centrosomes prior to the onset of mitosis (By similarity).
Synonyms: KIAA0699; SMALED2; SMALED2A; SMALED2B; bA526D8.1
Tractability: Antibody: its Gene Ontology location is reachable by antibodies, with high confidence. PROTAC: ubiquitination databases record sites on it; its protein half-life has been measured.
Gene: Protein-coding gene on chromosome 9 (92,711,363 to 92,764,833, reverse strand). Ensembl gene ENSG00000185963.
Subcellular location: Golgi apparatus; Cytoplasm, cytoskeleton; Cytoplasm; Nucleus envelope; Nucleus, nuclear pore complex
Subcellular location (Human Protein Atlas): Cytosol; Golgi apparatus; Plasma membrane
Pathways (Reactome):
Vesicle-mediated transport: COPI-independent Golgi-to-ER retrograde traffic
Gene Ontology:
Molecular function: protein binding; dynactin binding; dynein complex binding; dynein light intermediate chain binding; small GTPase binding; cytoskeletal anchor activity
Biological process: centrosome localization; protein localization to Golgi apparatus; regulation of microtubule cytoskeleton organization; retrograde vesicle-mediated transport, Golgi to endoplasmic reticulum; microtubule anchoring at microtubule organizing center; microtubule-based movement; minus-end-directed organelle transport along microtubule
Cellular component: annulate lamellae; centrosome; cytoplasm; Golgi apparatus; nuclear envelope; nuclear pore; cytoplasmic vesicle; cytosol; cytoskeleton
Genetic constraint (gnomAD): Loss-of-function variants: 25 observed, 68.86 expected, observed/expected ratio (o/e) 0.36, 90% interval 0.26 to 0.51. The upper end of that interval is the gene's LOEUF score, 0.51, which puts it in group 2 of 6, group 1 being the genes least tolerant of losing a copy. Missense variants: 894 observed, 1,188.5 expected, observed/expected ratio (o/e) 0.75, 90% interval 0.71 to 0.8. Synonymous variants: 501 observed, 513.82 expected, observed/expected ratio (o/e) 0.98, 90% interval 0.9 to 1.05.
Homologues: Orthologues: macaque BICD2 (99% identical), guinea pig BICD2 (95% identical), mouse Bicd2 (95% identical), rabbit BICD2 (92% identical), rat Bicd2 (91% identical), chimpanzee BICD2 (91% identical), pig BICD2 (90% identical), dog BICD2 (90% identical), zebrafish BICD2 (61% identical), Drosophila melanogaster BicD (37% identical), Caenorhabditis elegans bicd-1 (28% identical). Paralogues in human: BICD1 (62% identical).
Diseases named in the same sentence as BICD2 in open-access papers:
BICD2 is named in the same sentence as 50 diseases in open-access papers, as found by Europe PMC text mining. Sharing a sentence is not in itself a finding about the gene and the disease. The quoted sentences say what the papers report.
spinal muscular atrophy (17 papers, 2014 to 2025). A motor neuron disease that affect the muscles, and characterized by muscle weakness and atrophy resulting from progressive degeneration and irreversible loss of the anterior horn cells in the spinal cord (i.e., lower motor neurons) and the brain stem nuclei. "The importance of BICD2 in dynein-mediated transport is highlighted by the fact that mutations in this gene are associated with a type of spinal muscular atrophy (SMA)." (PMID 41334889, 2025). "Several human disease mutations causing spinal muscular atrophy and other neuromuscular diseases are located in the cargo-binding site of BicD2 and affect the affinity to distinct cargoes in a distinct manner." (PMID 38719748, 2024). "Type 2 spinal muscular atrophy with lower extremity dominance (SMALED2) is caused by bicaudal D cargo adaptor 2 (BICD2) variants." (PMID 39183348, 2024). "De novo heterozygous pathogenetic variant in BICD2 gene, associated with spinal muscular atrophy (SMA)." (PMID 38671719, 2024). "Most of BICD2 mutations have been found to cause Spinal Muscular Atrophy with Lower Extremity Dominance 2 (SMA-LED2), characterized by slowly progressive muscle wasting, and weakness in the lower extremities." (PMID 36930595, 2023). "BICD2 variants have been linked to neurodegenerative disorders like spinal muscular atrophy with lower extremity predominance (SMALED2) or hereditary spastic paraplegia (HSP)." (PMID 37047781, 2023). "Along this line, pathogenic variants within the BICD2 gene have been described as the cause of spinal muscular atrophy with lower extremity predominance 2 (SMALED2) and hereditary spastic paraplegia (HSP)." (PMID 37047781, 2023). "Mutations in BICD2 gene have been found to cause brain developmental defects, as well as other disorders, like Spinal Muscular Atrophy with Lower Extremity Dominance 2 (SMA-LED2)." (PMID 36930595, 2023). "Mutations in the human BICD2 gene have been found to cause an autosomal dominant form of spinal muscular atrophy (SMA-LED2), and brain developmental defects." (PMID 36930595, 2023). "Mutations in human BICD2 have been linked to a spectrum of neuronal disorders and particularly to a dominant mild early onset form of spinal muscular atrophy." (PMID 36068540, 2022). "The importance of BICD2 has recently been emphasised by the association of mutations in the human gene with dominant spinal muscular atrophy." (PMID 24986880, 2014). "In ClinVar, an in-frame deletion variant at the same location as the variant in Case 1, NM_001003800.2 (BICD2):c.2200_2202del (p.Lys734del) (Variation ID: 982816), is registered as likely pathogenic and causes childhood-onset proximal spinal muscular atrophy with contractures." (PMID 39183348, 2024). "The importance of these BicD2-dependent transport pathways is underscored by the fact that mutations of BicD2 cause brain and neuromuscular developmental diseases, including a subset of cases of spinal muscular atrophy, which is the most common genetic cause of death in infants." (PMID 37892127, 2023). "In addition, some individuals with spinal muscular atrophy caused by the BICD2 ‘hot spot’ mutation, c.302C > T:p.Ser107Leu, presented with unexpected heart failure-associated symptoms and exertional and supine dyspnoea." (PMID 36068540, 2022). "BICD2 has been recently reported as the causative gene for spinal muscular atrophy in human." (PMID 26306008, 2015). "There wassome degree of overlap with spinal muscular atrophy with lower extremity predominance causedby variants in DYNC1H and BICD2." (PMID 33559681, 2021). "Interestingly, most BICD2 missense variants have been associated with human spinal muscular atrophy (SMA) without obvious brain malformations." (PMID 32665036, 2020).
Lissencephaly (6 papers, 2020 to 2025). A spectrum of malformations of cortical development caused by insufficient neuronal migration that subsumes the terms agyria, pachygyria and subcortical band heterotopia. "To date, no prenatal brain anomalies have been reported in association with BICD2 variants, whereas postnatal cases have included cerebellar hypoplasia and lissencephaly." (PMID 41249097, 2025). "Recently, a novel de novo BicD2 nonsense mutation, K775X, was identified in a patient with lissencephaly." (PMID 39519078, 2024). "More recently, a C-terminally truncated Lissencephaly-associated form of BICD2 (K775X) was found to disrupt Nesprin-2 binding and to cause a severe defect in post-mitotic neuronal migration in mouse cerebral cortex." (PMID 36930595, 2023). "This is the first report of lissencephaly and cerebellar hypoplasia seen in a patient with homozygous loss-of-function variant in BICD2 that recapitulated the animal model." (PMID 35896821, 2022). "We describe a novel lissencephaly and cerebellar hypoplasia disease and associate it with a recessive variant in the BICD2 gene." (PMID 35896821, 2022). "It was postulated that defects in nuclear translocation that occur in the post-mitotic neuronal migration stage to be the mechanism of lissencephaly resulting from BICD2 truncating variant." (PMID 35896821, 2022). "Although BICD2 is essential for the proper development of the cerebral cortex but there have been no other clinical reports of individuals with loss of-function variants in BICD2 showing lissencephaly and cerebellar hypoplasia." (PMID 35896821, 2022). "In this study, we identified the first de novo BICD2 nonsense variant p.(Lys775Ter) in a patient presented with posterior predominant lissencephaly and SBH." (PMID 32665036, 2020). "Using whole exome sequencing (WES), we identified a novel nonsense BICD2 variant p.(Lys775Ter) (K775X) from a lissencephaly patient." (PMID 32665036, 2020). "In the current study, we showed that the interaction between BicD2 and Nesprin-2 is disrupted by the lissencephaly-associated p.(Lys775Ter) variant." (PMID 32665036, 2020). "In conclusion, we identified a novel de novo truncated BICD2 variant in a posterior predominant lissencephaly patient." (PMID 32665036, 2020). "Our study reports the first disease-causing BICD2 nonsense variant in lissencephaly." (PMID 32665036, 2020). "Therefore, our results suggested that BicD2 K775X exerted a dominant-negative effect on neuronal migration, which may underlie the pathological mechanism of lissencephaly." (PMID 32665036, 2020). "This evidence indicates that the BicD2-Nesprin-2 pathway is crucial for normal cortical development, and its abnormalities can lead to lissencephaly." (PMID 39519078, 2024). "Our report supports that BICD2 should be considered in the differential diagnosis for patients with lissencephaly and cerebellar hypoplasia Additional clinical features of BICD2 are likely to emerge with the identification of additional patients." (PMID 35896821, 2022). "Here we identified a novel de novo BICD2 nonsense variation p.(Lys775Ter) (K775X) from a lissencephaly patient using whole-exome sequencing (WES)." (PMID 32665036, 2020). "Here we identified the first disease-causing truncated BICD2 pathogenic variant, which led to SMALED2 and lissencephaly, further supporting the role of BICD2 in human brain development." (PMID 32665036, 2020). "However, lissencephaly and cerebellar hypoplasia are consistent with that observed after BICD2 knockdown in mice showing defects in laminar organization of the cerebral cortex, hippocampus and cerebellar cortex, indicative of radial neuronal migration defects." (PMID 35896821, 2022). "Therefore, we considered BICD2 to be a convincing candidate gene in the context of lissencephaly and cerebellar hypoplasia." (PMID 35896821, 2022). "Moreover, a BICD2 nonsense variation p.(Lys775Ter) was identified in a boy with lissencephaly and subcortical band heterotopia." (PMID 35896821, 2022).
Lissencephaly (continued). "Our results uncover a novel mechanism of lissencephaly by defects in nuclear translocation (but not centrosome movement) during neuronal migration resulting from BICD2 truncated variant." (PMID 32665036, 2020). "DYNC1H1 is known to bind both bicd cargo adaptor (BICD2), a microtubule motor adaptor associated with SMA lower extremity–predominant 2, and lissencephaly 1 (LIS1), a dynein regulator associated with MCD/lissencephaly, which might explain why the variant of DYNC1H1 could lead to pachygyria or MCD." (PMID 34803881, 2021).
autosomal dominant lower extremity-predominant spinal muscular atrophy 2 (5 papers, 2020 to 2025). "Mutations in one of these activating adaptors, Bicaudal-D2 (BICD2), are associated with a neurodegenerative disease called Spinal Muscular Atrophy with Lower Extremity Predominance (SMALED2)." (PMID 41334889, 2025). "In support, muscle-targeted knockout of BICD2, the causative factor of Spinal Muscular Atrophy Lower Extremity Predominant (SMALED), a lower motor neuron disease, was found to be a major driver of the motor neuron loss in a mouse model." (PMID 37360176, 2023). "Dominant missense variants in the Bicaudal D2 Drosophila homolog 2 (BICD2) gene were initially described in autosomal dominant lower extremity-predominant spinal muscular atrophy 2 (SMALED2A;MIM#609797) and its prenatal onset form (SMALED2B, MIM #618291)." (PMID 35896821, 2022). "Interestingly, heterozygous missense variants in human BICD2 cause autosomal dominant lower extremity-predominant spinal muscular atrophy 2 (SMALED2; MIM # 615299), which presents a loss of spinal motor neurons, muscle weakness, and atrophy predominantly of the lower limbs." (PMID 32665036, 2020).
neuropathy (4 papers, 2015 to 2025). A disorder affecting the nervous system that manifests with pain, tingling, numbness, and/or muscle weakness. "Early onset lower extremity predominant motor symptoms jointly with Achilles contracture urged us to exclude the recently reported bicaudal D homolog 2 (BICD2)-related neuropathy." (PMID 26032230, 2015).
HIV-1 infection (3 papers, 2017 to 2025). The type species of lentivirus and the etiologic agent of acquired immunodeficiency syndrome (AIDS). "Our work on HIV-1 reconstitution with dynein expands our understanding of HIV-1 trafficking and is consistent with the initial studies that linked BicD2 to HIV-1 infection." (PMID 40532013, 2025). "BicD2 was initially identified as a cellular co-factor for HIV-1 infection in one of the 3 genome-wide screens developed using either shRNA or siRNA published in 2008." (PMID 32344581, 2020).
polymicrogyria (3 papers, 2019 to 2023). A developmental brain abnormality characterized by an excessive amount of small convolutions on the surface of the brain and cognitive dysfunction. "R694C is a recurrent BICD2 mutation that causes a severe form of congenital polymicrogyria with impaired neuronal migration." (PMID 36930595, 2023). "Also, cortical expression of the polymicrogyria-causing BICD2 R694C mutation caused delayed migration of postmitotic neurons within the cortical plate, but the underlying molecular defect causing the delay remains unknown." (PMID 36930595, 2023). "Interestingly, missense BICD2 variant p.Arg694Cys has been reported in two patients of arthrogryposis multiplex congenita and cortical malformations, including microcephaly and bilateral perisylvian polymicrogyria." (PMID 32665036, 2020). "As such, BICD2 seems associated with human malformations in cortical developments such as polymicrogyria (PMG), and the spectrum of BICD2-associated malformations overlaps with the wide spectrum of developmental abnormalities found in patients with DYNC1H1 mutations." (PMID 31655624, 2019). "However, most patients with heterozygous missense BICD2 variants did not exhibit obvious CNS malformation except two cases of polymicrogyria." (PMID 32665036, 2020).
chronic rhinosinusitis (2 papers, 2017 to 2019). Chronic form of sinusitis. "HLA-DRA has been associated with chronic rhinosinusitis with nasal polyps in previous studies and HLCS, BICD2, VSIR and SLC5A1 may be new targets for future research." (PMID 29253858, 2017). "Comparisons with data from expression quantitative trait loci showed the most skewed allelic distributions in cases with chronic rhinosinusitis with nasal polyps compared with controls for the genes HLCS, HLA-DRA, BICD2, VSIR and SLC5A1." (PMID 29253858, 2017). "Our study indicates that HLCS, HLA-DRA, BICD2, VSIR and SLC5A1 could be involved in the pathogenesis of chronic rhinosinusitis with nasal polyps." (PMID 29253858, 2017). "This study suggests that HLA-DRA as well as four additional genes; HLCS, VSIR, BICD2 and SLC5A1, which have not been previously identified as associated with chronic rhinosinusitis with nasal polyps, could be important for the development of this disease." (PMID 29253858, 2017).
hereditary spastic paraplegia (2 papers, 2015 to 2023). Hereditary spastic paraplegias (HSP) comprise a genetically and clinically heterogeneous group of neurodegenerative disorders characterized by progressive spasticity and hyperreflexia of the lower limbs. "As mutations of the kinesin-1-encoding gene KIF5A were linked to manifestation of familial hereditary spastic paraplegia, it can be assumed that altered interactions of BICD2 with kinesin 1 are resulting in a different pathophysiology that is associated with HSP." (PMID 37047781, 2023). "Recently, we and others have identified heterozygous mutations in BICD2 as causative for autosomal dominant SMA, lower extremity-predominant, 2 (SMALED2) and hereditary spastic paraplegia (HSP)." (PMID 26594138, 2015).
Hydrocephalus (2 papers, 2020 to 2025). Hydrocephalus is an active distension of the ventricular system of the brain resulting from inadequate passage of CSF from its point of production within the cerebral ventricles to its point of absorption into the systemic circulation. "The results showed that Cp110 depletion significantly rescued the phenotypic defects induced by Bicd2 knockdown, including curved body, pericardial edema, abnormal otoliths, and hydrocephalus." (PMID 41102520, 2025). "In our patient, the brain also showed slight hydrocephalus and microcephaly, also consistent with potential roles of BICD2 in earlier stages." (PMID 32665036, 2020).
juvenile amyotrophic lateral sclerosis (2 papers, 2023 to 2024). Juvenile amyotrophic lateral sclerosis (JALS) is a very rare severe motor neuron disease characterized by progressive upper and lower motor neuron degeneration causing facial spasticity, dysarthria, and gait disorders with onset before 25 years of age. "BICD2 mutation has been extensively researched and linked with spinal muscular atrophy type 2 and juvenile amyotrophic lateral sclerosis." (PMID 37109658, 2023).
muscular atrophies (2 papers, 2019 to 2024). "Further co‐immunostaining studies are crucial to decipher the nature of extra‐muscular cells presenting with increased NEFM abundance in (VWA1‐ and BICD2‐related) neuromyopathies and neurogenic muscular atrophies." (PMID 38652110, 2024).
nasal polyps (2 papers, 2017 to 2019). "BICD2 is over-expressed in nasal polyps and up-regulating alleles more common in controls and down regulating slightly more common in cases." (PMID 29253858, 2017).
viral infection (2 papers, 2020 to 2024). "As BICD2 acts as a dynein adaptor and dynein is necessary for HPV entry, we then asked if the dynein cargo adaptor BICD2 plays a role in virus infection." (PMID 38829892, 2024). "Five days after the viral infection, BicD2 expression in shBicD2-transduced cells was significantly lower (shBicD2–3’U: 13.3 ± 0.03% and shBicD2-CDS: 10.0 ± 0.01%) compared to the control cells infected with lentivirus expressing non-targeting shRNA (shCtrl)." (PMID 32665036, 2020). "Similarly, our results showed that depletion of the dynein adaptor protein BICD2 blocked HPV infection in multiple cell types, indicating that BICD2 is also crucial during virus infection." (PMID 38829892, 2024).
asthma (1 paper, 2017). "HLCS, BICD2, and SLC5A1 have not been connected to asthma, VSIR was implicated with lung function decline in non-asthmatic patients in a genome-wide study published in 2012 but this association could not be confirmed by replication." (PMID 29253858, 2017).
autosomal recessive dHMN (1 paper, 2016). "Two heterozygous variants were detected in genes associated with autosomal dominant spinal muscular atrophy and CMT2 (BICD2 and TRPV4) and one homozygous variant was detected in SIGMAR1, a gene associated with autosomal recessive dHMN and juvenile ALS." (PMID 27629094, 2016).